PRAMEF15 (PRAME family member 15)
Synonyms: OTTHUMG00000007921
Tractability: No criterion of Open Targets' tractability assessment is met for any kind of drug.
Gene: Protein-coding gene on chromosome 1 (13,315,581 to 13,322,598, forward strand). Ensembl gene ENSG00000204501.
Gene Ontology:
Molecular function: ubiquitin-like ligase-substrate adaptor activity
Biological process: proteasome-mediated ubiquitin-dependent protein catabolic process; negative regulation of apoptotic process; negative regulation of cell differentiation; negative regulation of DNA-templated transcription; positive regulation of cell population proliferation; protein ubiquitination
Cellular component: Cul2-RING ubiquitin ligase complex; cytoplasm
Genetic constraint (gnomAD): Loss-of-function variants: 21 observed, 25.73 expected, observed/expected ratio (o/e) 0.82, 90% interval 0.58 to 1.18. The synonymous counts are far from expectation, so gnomAD's model fits this gene poorly and the ratio says little. Missense variants: 356 observed, 410.04 expected, observed/expected ratio (o/e) 0.87, 90% interval 0.8 to 0.95. Synonymous variants: 118 observed, 155.98 expected, observed/expected ratio (o/e) 0.76, 90% interval 0.65 to 0.88.
Homologues: Orthologues: mouse Pramel13 (46% identical), rat Pramef12 (44% identical), rat Pramef8 (44% identical), mouse Pramel12 (43% identical), mouse Pramel15 (43% identical), rat LOC120103107 (43% identical), mouse Pramel16 (42% identical), mouse Pramel31 (42% identical), rat Pramef5 (42% identical), rat Pramef20l1 (42% identical), rat Pramel36l1 (42% identical), mouse Gm13040 (42% identical), and 78 more. Paralogues in human: PRAMEF4 (98% identical), PRAMEF9 (97% identical), PRAMEF25 (97% identical), PRAMEF26 (97% identical), PRAMEF5 (97% identical), PRAMEF11 (97% identical), PRAMEF27 (97% identical), PRAMEF6 (97% identical), PRAMEF20 (82% identical), PRAMEF12 (62% identical), PRAMEF8 (62% identical), PRAMEF7 (62% identical), and 12 more.